CELF2-AS1 (CELF2 antisense RNA 1)
Synonyms: FLJ40494; Em:AC026887.2; formerly C10orf31
Gene: Long non-coding RNA gene on chromosome 10 (11,274,391 to 11,344,799, reverse strand). Ensembl gene ENSG00000181800.
Subcellular location: Secreted
Diseases named in the same sentence as CELF2-AS1 in open-access papers:
CELF2-AS1 is named in the same sentence as 1 disease in open-access papers, as found by Europe PMC text mining. Sharing a sentence is not in itself a finding about the gene and the disease. The quoted sentences say what the papers report.
non-small cell lung carcinoma (1 paper, 2024). A group of at least three distinct histological types of lung cancer, including non-small cell squamous cell carcinoma, adenocarcinoma, and large cell carcinoma. "CELF2-AS1 (CELF2 Antisense RNA 1) (average methylation 80%, p = 0.02) suppresses non-small cell lung carcinoma growth by inhibiting the PREX2-PTEN interaction, which regulates cell proliferation." (PMID 38791918, 2024).